CXCL12 (C-X-C motif chemokine ligand 12)
Diseases named in the same sentence as CXCL12 in open-access papers (continued):
Sharing a sentence is not in itself a finding about the gene and the disease.
tumor (continued). "In an orthotopic and CXCL12-producing environment, CXCR7 was not able to suppress the growth of large, established tumors, as growth curve slopes of both NB8×4 and NB8×4×7 cell-derived tumors were similar in the exponentially tumor growth phase." (PMID 22916293, 2012). "Only when these stromal sects are detected, immunoreactivity for CXCL-12 is associated to the stromal cells and this is not greatly different in control or PICP treated tumor, leading us to suggest that all the effects of PICP we have detected are independent from CXCR4/CXCL-12 signaling." (PMID 19226458, 2009). "The number of SN12C-VC or SN12C-VHL-KD tumor cells undergoing proliferation or apoptosis, as determined by PCNA and TUNEL staining, respectively, was not significantly different between the anti-CXCL12 and the control antibody treated mice." (PMID 17083723, 2006). "Interestingly, it has been demonstrated that both RCC cell lines and human RCC tumor specimens express elevated levels of CXCR4, but not its ligand CXCL12, as compared to normal kidney specimens." (PMID 17083723, 2006). "However, autocrine CXCL12 is not the main initiator of CAF contractility, highlighting its distinct functions in promoting a permeable endothelium that is more prone to angiogenesis and tumor cell intravasation." (PMID 38455762, 2024). "Since synergistic effects of CXCL12 and CXCL11 on tumor cell migration do not correlate with the selective use of distinct chemokine receptors / receptor combinations, we asked whether additive effects would correlate with receptor-activated signaling pathways." (PMID 36539774, 2022). "We sequentially extracted the tumor specimens with Nonidet P-40, sodium deoxycholate (DOC), DNase, and sodium dodecyl sulfate (SDS) and analyzed the lysates by SDS-polyacrylamide gel electrophoresis (SDS-PAGE) and immunoblotting with anti-KRT19 and anti-CXCL12 antibodies." (PMID 35046049, 2022). "Interestingly, CXCL12 enhances the expression of VE-cadherin, matrix metalloproteinase 2 (MMP2) and laminin5γ2 via CXCR4 in tumor cells (rather than endothelial cells), forming vascular-like channels that promote vascular mimicry (VM) formation and provide blood perfusion for HCC tissues." (PMID 34386499, 2021). "Although CXCR4 plays a significant role in tumor growth, angiogenesis, invasion and metastasis, long-term blockade of CXCR4 might yield severe adverse effects relating to prenatal death in mice lacking CXCL12, as it may spare the normal tissues." (PMID 33129326, 2020). "In the present study ACKR3 was genetically deleted on the tumor cells while the receptors expressed on mouse tissue were not inhibited, suggesting that expression of ACKR3 on VAL cells was required for spreading via lymphatics but was independent of elevated CXCL12 levels." (PMID 29156704, 2017). "CXCL12 or stromal cell-derived factor 1, a chemokine with pleiotropic functions, including the attraction of inflammatory cells, was expressed outside malignant nodules, but its receptor CXCR4 was expressed by tumor cells, though not on infiltrating CD8+ cells." (PMID 25866902, 2015). "However, even though LA cells expressed higher levels of CXCL12, we did not observe any significant increase in the expression of matrix metalloproteinases (MMP) and other enzymes capable of degrading extracellular matrix, which are typical cellular signature of senescent tumor cells." (PMID 33154552, 2020).
cancer (1,659 papers, 2003 to 2026). A tumor composed of atypical neoplastic, often pleomorphic cells that invade other tissues. "Our comprehensive investigations linked CXCL12 expression to prognosis, DNA methylation, immune cell influx, genetic alterations, and microsatellite stability across various cancers." (PMID 40166682, 2025). "CXCL12 emerges as a predictive marker for cancer progression across various tumors and is associated with inflammatory response." (PMID 40166682, 2025). "We evaluated the diagnostic and predictive implications of CXCL12 expression in varied forms of cancer, together with delineating its variation in various immune cell subsets therein." (PMID 40166682, 2025). "CXCL12 is an essential chemokine linked to cancer cell proliferation, inflammation, and immunological suppression." (PMID 40584290, 2025). "CXCR4 overexpression is usually correlated with poor prognosis and often associated with metastasis, that depends on the CXCL12-mediated promotion of cancer stem cells migration and invasion." (PMID 40307933, 2025). "Recent studies have indicated that the CXCL12 gene polymorphisms are associated with several cancer risks, including urogenital system cancers, lung cancer, nasopharyngeal carcinoma, and colorectal cancer." (PMID 39703847, 2024). "The first recruited motile streaming TAMs differentiate into CXCR4-expressing macrophages in a TGF-β-dependent manner and cooperate with CXCL12-expressing cancer-associated fibroblasts in the perivascular niche to promote cancer cell intravasation." (PMID 39516356, 2024). "Accordingly, understanding the complicated mechanisms underlying tumorigenesis, progression, and the role of the CXCL12/CXCR4 axis in these processes is essential for emerging targeted therapeutic interventions in cancer therapy." (PMID 39070795, 2024). "High-stromal tumors have a lower fraction of certain T cells, natural killer (NK) cells, and macrophages, and increased expression of CXCL12 in epithelial cancer cells and cancer-associated mesenchymal stem cells (CA-MSCs)." (PMID 38182756, 2024). "This implies that the expression of CXCL12 was related to the activation of microglia caused by cancer pain." (PMID 39641645, 2024). "For instance, cancer-associated fibroblasts (CAFs) release CXCL12 (C-X-C motif chemokine ligand 12) to facilitate EMT by cancer cells." (PMID 39329988, 2024). "By utilizing this model system, we unveiled underlying cancer PDAC cell-intrinsic C-X-C motif chemokine 12 (CXCL12) expression contributing to T cell-mediated cytotoxicity in a CXCL12/CXC chemokine receptor 4 (CXCR4)-dependent manner." (PMID 38654067, 2024). "CXCR4 and its ligand, CXCL12, are immunohistochemically overexpressed in gastric cancer compared with normal gastric tissue and are associated with cancer cell survival, proliferation, angiogenesis, and migration." (PMID 39003350, 2024). "This upregulation subsequently augments CXCL12 expression, thereby facilitating the transformation of normal fibroblasts into cancer-associated fibroblasts (CAFs)." (PMID 38920657, 2024). "In the TME, CXCL12 is mainly expressed by cancer-associated fibroblasts (CAFs), but endothelial cells and cancer cells can also produce CXCL12." (PMID 37966614, 2023). "The relationship between clinical parameters and the sum of CXCL12 expression intensity in both cancer cells and cancer-associated fibroblasts was assessed." (PMID 37227446, 2023). "CXCL12 is a chemokine released by cancer-associated fibroblasts, tumors, and normal cells that promotes the motility and migration of cancer cells expressing its membrane receptor CXCR4." (PMID 37227446, 2023). "Our study showed that curcumin is a potent anti-cancer agent that can remodel the breast TME, thereby restricting the ADMSC-cancer positive feedback loop associated with the CXCL12/CXCR4 axis." (PMID 38004606, 2023).
cancer (continued). "In a model of pancreatic ductal adenocarcinoma (PDAC), inhibiting the CXCL-12/CXCR4 axis mediated by cancer-associated fibroblasts (CAFs) using the CXCR4 inhibitor AMD3100 resulted in enhanced accumulation of T cells and regression of cancer." (PMID 37511431, 2023). "Further, an upregulation of CXCR4, the receptor of the cytokine CXCL12 (known to exclude T-cells in cancer) was linked to increased CXCL12 and a downregulation of NF-kappa-B inhibitor zeta (NFKBIZ) in fibroblast foci." (PMID 38012580, 2023). "The expression of this receptor in cancer cells has also been linked to metastasis to tissues with high C-X-C motif chemokine 12 (CXCL12)-concentration, e.g., lungs, liver and bone marrow." (PMID 37047331, 2023). "This study revealed that increased ketogenesis suppressed KLF-5 dependent CXCL12 signaling, which is implicated in the growth and metastasis of cancer cells." (PMID 37692839, 2023). "CCL5 and CXCL12 have been linked to cancer progression, epithelial–mesenchymal transition, immune evasion, metastasis, and worse prognosis." (PMID 36613922, 2022). "The expression of chemokine (C-X-C motif) receptor 4(CXCR4) in cancer cells is associated with increased expression of chemokine ligand CXCL12 in LSECs’ microenvironment and CXCR4-CXCL12 signaling drives metastasis." (PMID 36387238, 2022). "Patients with positive CXCL12 expression in residual survival cancer cells displayed a positive association with worse FFR in univariate and multivariate Cox proportional hazard regression analysis (p = 0.005 and p = 0.031, respectively)." (PMID 34976180, 2022). "Blocking the CXCR4/CXCL12 signalling axis promotes T-cell accumulation and acts synergistically with anti-PD-L1 to cause cancer regression." (PMID 36284271, 2022). "For example, cancer-induced reprogrammed fibroblasts (CAFs) produce CXCL12, which contributes to cancer progression by further mobilizing bone marrow-derived cells in cancer tissue and promoting angiogenesis associated with cancer growth." (PMID 36097044, 2022). "Among the chemokines reported in oncovirus-associated cancers, CCL2 and CXCL12 are known to directly support cancer cell stemness, proliferation, and survival." (PMID 35159113, 2022). "CXCL12 expression in cancer cells is associated with worse progression-free survival in stage III EOC patients, and deserves further attention as a potential prognostic and therapeutic target." (PMID 35406620, 2022). "CXCL12 has been associated with progression in multiple types of cancer; however, its prognostic potential in EOC remains controversial." (PMID 35269786, 2022). "In malignant neoplasms, a higher expression of CXCL12 has been associated with more aggressive biological behaviors." (PMID 35582358, 2022). "Meanwhile, TGF-β activated the fibroblasts to form cancer-associated fibroblasts (CAFs) that secrete higher CXCL12 levels, which bound to its cognate receptor CXCR4 on M2 macrophages." (PMID 35853880, 2022). "We first compared the response of LAP0297 cells to LPA, S1P, and SDF-1 (CXCL12), agonists of Gi-coupled receptors that have been implicated in cancer cell dissemination." (PMID 34808208, 2022). "This cancer seems to be promoted by the amplified repression of CXCL12, mediated by the rs12416605 ancestral C allele, which makes C-allele carriers more susceptible to develop GC metastasis." (PMID 35249174, 2022). "The main tumor-promoting factor secreted by cancer associated fibroblasts is CXCL-12, which is also a component of SASP." (PMID 34746270, 2021). "Prior evidence suggests that mesenchymal stromal cells, such as cancer-associated fibroblasts (CAFs) and possibly mural cells coating the blood vasculature, serve as the primary source of CXCL12 production and secretion." (PMID 33927723, 2021). "In triple negative breast cancer (TNBC), CXCL12 from cancer-associated fibroblasts is found to select cancer cells with high Src activity homing to the bone." (PMID 34745140, 2021).
cancer (continued). "The activated fibroblasts (aPSCs and/or CAFs) of the TME are the predominant source of CXCL12 that facilitates the acquisition, maintenance, and enhancement of several cancer hallmark traits." (PMID 35008248, 2021). "In this review, we focus on one such chemokine, CXCL12, secreted by the cancer-associated fibroblasts and discuss its contribution to several of the classical hallmarks of PDAC and other tumors." (PMID 35008248, 2021). "Secretion of its ligand CXCL12 in cancer cells is sufficient to cause paracrine release in lungs but not in liver, thereby promoting progression of metastasis and worsening of the disease." (PMID 34298991, 2021). "Here, we observed that the serum levels of various chemokines, including CCL19, IL-8, CXCL1, CXCL12, and RANTEs, the latter of which has been associated with the recruitment of Tregs in cancer patients, were increased in BC patients." (PMID 30718502, 2019). "Increased levels of CXCR4/CXCL12 have been found in many types of cancer, including BC, and have been associated with metastasis and poor prognosis." (PMID 29849822, 2018). "The CXCR4/CXCL12 axis has been extensively associated with different types of cancer correlating with higher aggressiveness and metastasis." (PMID 29920526, 2018). "Further, the expression of yet another chemokine ligand CXCL16 allows PCa cells to recruit and convert CXCR6-expressing mesenchymal stem cells into cancer-associated fibroblasts that also secrete high levels of CXCL12/SDF1." (PMID 29967592, 2018). "In our previous study of methylation profiles in 206 BC patients we showed that the risk for LNMs development and higher proliferation of cancer cells was increased by hypermethylation of CXCL12 and ADAM23 genes, respectively." (PMID 30189837, 2018). "The activation of CXCL12/CXCR4 axis is associated with potential progression of cancer, such as invasion, metastasis and chemoresistance." (PMID 28176874, 2017). "Previous meta-analysis of genome-wide studies have indicated that the relationship between SNP rs1801157 of CXCL12 gene and cancer risk have some limitations due to their limited number of subjects and absence of different types of population in one study." (PMID 28929029, 2017). "CXCL12 is a chemokine secreted by cancer associated myofibroblasts and binds to the CXCR4 receptor on epithelial cells, enhancing their proliferation, migration, and invasion and thus playing a role in tumorigenesis." (PMID 28531107, 2017). "Downregulation of CXCL12 in cancer cells is frequently associated with promoter methylation, which encourages cells to migrate toward a CXCL12 gradient and establish metastases." (PMID 28666461, 2017). "Cancer-associated fibroblasts (CAFs) produce CXCL12, which protects cancer cells against CD8+T cell attack." (PMID 27259252, 2016). "It plays a role in a variety of cancer types, and has been linked with cancer cell proliferation and metastasis to bones and lymph nodes through both CXCL12 and MIF." (PMID 26347749, 2015). "Recently, the CXCL12 G801A polymorphism was shown to be associated with an increased risk of various kinds of cancers, but the results were too inconsistent to be conclusive." (PMID 25268356, 2014). "Odds ratios (ORs) and their 95% confidence intervals (CIs) were used to determine the strength of association between CXCL12 G801A polymorphism and cancer risk." (PMID 25268356, 2014). "We conducted the largest and most comprehensive quantitative meta-analysis of the relationship between CXCL12 G801A polymorphisms and cancer risk." (PMID 25268356, 2014). "The CXCL12 G801A polymorphism is associated with an increased risk of cancer based on current published data." (PMID 25268356, 2014).
cancer (continued). "A significant association between CXCL12 G801A polymorphism and cancer risk was found under all genetic models." (PMID 25268356, 2014). "Recently, numerous studies have shown that the CXCL12 G801A polymorphism occurs in different types of cancers, but the results have been too inconsistent to be conclusive." (PMID 25268356, 2014). "In order to resolve this controversy, the present meta-analysis, which included 4,435 cases and 6,898 controls from 30 case-control studies, explored the association between CXCL12 G801A polymorphism and cancer risk." (PMID 25268356, 2014). "Further, subgroup analysis stratified by ethnicity suggested a significant association between CXCL12 G801A polymorphism and cancer risk in the Asian subgroup under all genetic models." (PMID 25268356, 2014). "In conclusion, this meta-analysis suggested that CXCL12 G801A polymorphism was associated with an increased risk of cancer based on current published data." (PMID 25268356, 2014). "Since then, several additional studies of the CXCL12 G801A polymorphism and cancer risk were published." (PMID 25268356, 2014). "Our results indicated that CXCL12 G801A polymorphism was associated with an increased risk of cancers." (PMID 25268356, 2014). "Angptl4, Cxcl12 and Mdk, which are upregulated in our model, have all been implicated in cancer development and progression." (PMID 24039874, 2013). "Some of them are implicated in the development or progression of cancer, in particular the chemokine CXCL12 (also termed stromal cell-derived factor-1, SDF1) which binds to two receptors, the CXC receptor 4 (CXCR4) and the CXC receptor 7 (CCR7)." (PMID 24212636, 2011). "Carcinoma foci were of equal size in CXCL12-expressing cells depleted of Bim as chemokine-deficient wild-type HCT116 cells." (PMID 20877573, 2010). "CXCL12 producing carcinomas cultured on poly-HEMA displayed heightened Bim and loss of Mcl-1 and Bcl-2 preceding cytochrome c release, and caspase-9 activation." (PMID 20877573, 2010). "Therefore, CXCL12 not only helps cancer cells find the nest, but also improves tumor-associated inflammation, facilitating the establishment of a metastatic niche." (PMID 40076892, 2025). "Similarly, CXCL12, secreted by cancer associated fibroblasts, also recruits macrophages to the TME and promote more M2 polarisation." (PMID 40852716, 2025). "Furthermore, it was found that CXCR4-expressing TCSCs follow a chemokine gradient binding to stromal cell-derived factor-1 (SDF-1/CXCL12) released by cancer-associated fibroblasts (CAFs), which increases TCSCs invasiveness and promotes TC metastasis." (PMID 39776907, 2024). "The intricate interaction between ADMSCs and cancer cells not only drives the differentiation of ADMSCs into cancer-associated fibroblasts (CAFs) but also the metastasis of cancer cells, which is attributed to the CXCL12/CXCR4 axis." (PMID 38004606, 2023). "Likewise, signalling molecules tumour necrosis factor (TNF), transforming growth factor beta (TGFB1), and C-X-C motif chemokine 12 (CXCL12) were prominent drivers of downstream gene expression associated with multiple cancer hallmarks." (PMID 37370765, 2023). "Moreover, CXCR6 signaling stimulates the conversion of mesenchymal stem cells into cancer-associated fibroblasts, which secrete CXCL12." (PMID 35406450, 2022). "Interestingly, CXCL12 is known to be central to the development of many organs and more critically involved in pathophysiological processes underlying cancer, inflammation, and cardiovascular disorders." (PMID 35742971, 2022). "We showed that atypical chemokine receptor 3 (ACKR3), a receptor of the CXC motif chemokine 12 (CXCL12) implicated in cancer, inflammation, and cardiovascular disorders, is selectively expressed on the surface of senescent human fibroblasts but not on proliferating cells." (PMID 35742971, 2022).